TNF (tumor necrosis factor)
Diseases named in the same sentence as TNF in open-access papers (continued):
Sharing a sentence is not in itself a finding about the gene and the disease.
Arthritis (continued). "It works by reducing the activity of inflammation-causing molecules, such as inducible nitric oxide synthase (iNOS), cyclooxygenase-2 (COX-2), and tumor necrosis factor (TNF)-α, slowing down cartilage damage, and inhibiting matrix metalloproteinase (MMP)-2 and MMP-9 in rats with arthritis." (PMID 39838308, 2025). "Comparison of baseline cytokine levels median [IQR] for those with and without arthritis response to TNF-inhibitor therapy." (PMID 40170117, 2025). "Luteolin displayed potent anti-inflammatory activity in both in vitro and in vivo models of arthritis, where it inhibited NO, PGE2, and TNF-α production, downregulated COX-2 and iNOS expression, and reduced matrix metalloproteinases through blockade of NF-κB and MAPK signaling." (PMID 41304898, 2025). "Mice lacking SIGIRR are more susceptible to antigen-induced arthritis, which is attributed to increased production of TNF-α by memory CD4+ T cells, whereas ectopic expression of SIGIRR leads to decreased production of TNF-α." (PMID 40583347, 2025). "Inflammation further exacerbates this degeneration, as inflammatory cytokines, such as interleukin‐1 beta (IL‐1β), IL‐6, IL‐18 and tumour necrosis factor‐alpha (TNF‐α), promote ECM degradation, highlighting inflammation as a critical driver of arthritis pathogenesis." (PMID 40179133, 2025). "Anti-LTα3 reduced arthritis only in TNF-KO mice, indicating that the effect of LTα3 was visible in the absence of TNF." (PMID 40650132, 2025). "An integrated analysis of transcriptomics and chromatin accessibility in human monocytes stimulated with prostaglandin E2 (PGE2) and TNF revealed that PGE2 increased the expression of 41% of TNF-inducible genes, indicating heightened synovial inflammation in RA and ICI-induced arthritis clinically." (PMID 41239350, 2025). "Prolonged exposure to pro-inflammatory cytokines, such as interleukin-1β (IL-1β), tumor necrosis factor-alpha (TNF-α), and interleukin-6 (IL-6) exacerbates inflammation by attracting more immune cells to the affected tissue, worsening conditions such as joint inflammation." (PMID 41242067, 2025). "For instance, in a collagen-induced model of arthritis, treatment with a GSK3 inhibitor reduced joint inflammation and leukocyte infiltration and decreased the production of proinflammatory cytokine such as IL-1β, TNF, IL-6, and IFN-γ." (PMID 39923112, 2025). "In the two cases analyzed, TNF-α inhibitors relieved mild symptoms (fever, rash) but did not improve more severe complications such as papilledema or arthritis." (PMID 41333465, 2025). "In addition, MSCs overexpressing HDAC5 successfully prevented TNF-α-induced impairment of immunosuppressive function and improved therapeutic effects in an SKG arthritis model." (PMID 41436435, 2025). "Apart from the powerful bone-resorbing agents such as TNF-α, IL-1, and IL-6, GGT may also have a role in the pathological expression of RANKL during arthritis." (PMID 40362197, 2025). "Lactobacillus treatment can prevent the onset of arthritis in preclinical models, reduce arthritis scores in CIA rat and pro-inflammatory cytokines (such as IL-17, IL-1β, IL-6, and TNF-α), and increase the release of anti-inflammatory cytokines like IL-4 and IL-10 in bodily fluids." (PMID 40692793, 2025). "The combined intervention of TNF antagonists and iron death inducers can effectively induce iron death in FLS cells, thereby significantly weakening the disease progression of collagen induced arthritis models." (PMID 38482018, 2024). "In this study, it was observed that ROSA could lower TNF-α expression levels, suggesting that ROSA may have the potential to alleviate CHIKV-induced arthritis." (PMID 38800832, 2024). "Moreover, miR-7-5p inhibits the TNF-α/NF-κB signaling pathway by binding to the 3’-UTR of p65, resulting in diminished production of inflammatory cytokines and alleviating arthritis severity." (PMID 39530095, 2024).
Arthritis (continued). "In arthritis patients with less gingival inflammation indicated by lower GI, TNF-α is probably not the major inducer of either periodontitis or RA." (PMID 38256582, 2024). "The patient was treated with prednisolone (5–10 mg/day) and human IgG1 monoclonal antibody specific for tumor necrosis factor-α (TNF-α, adalimumab) at a dose of 40 mg once every two weeks, which was introduced 2 years ago to treat arthritis and reduce the adverse effects of steroids." (PMID 38933100, 2024). "Moreover, we conducted in vivo studies and showed that propionate monotherapy or a combination of propionate with an anti-TNF DMARD, achieved desirable therapeutic efficacy for arthritis." (PMID 38782893, 2024). "RvD1 could also reduce the expression of TNF-α, RANKL, and TRAP and reduce bone destruction in mice with joint inflammation." (PMID 39861667, 2024). "Using a dominant-negative mutant of TNF (DN-TNF) to block sTNF while excluding tmTNF attenuates arthritis without suppressing innate immunity to Listeria monocytogenes." (PMID 37196131, 2024). "The rat model of arthritis also exhibited significant inflammatory response, and peptide BG can significantly inhibit serum pro-inflammatory factor levels, including IgM-RF, CRP, IL-1β, IFN-γ, and TNF-α." (PMID 39669913, 2024). "A certain level of inflammation is maintained; however, it was not a full-blown inflammatory environment like those in arthritis, as demonstrated by the lack of a high level of TNF-alpha and IL-1 in the blood." (PMID 37509659, 2023). "The mechanism of anti-arthritis effects might relate to the regulation of the inflammatory pathway with cyclooxygenase 2 (COX-2) and tumor necrosis factor (TNF-α) altered." (PMID 37630377, 2023). "WFR could effectively alleviate the arthritis symptoms of CIA rats; reduce the levels of IL-6, IL-1β, and TNF-α in the peripheral blood of CIA rats; and inhibit the expression of MMP3 and fibronectin." (PMID 38098062, 2023). "Furthermore, it has been shown that cachexia, arthritis, and autoimmunity developed by TTP-KO mice were prevented if they were early treated with TNFα antibodies." (PMID 38274271, 2023). "Therefore, TNF-α may not play a central role in KD-associated arthritis." (PMID 37336934, 2023). "Although OA is a noninflammatory form of arthritis, we found that pro-inflammatory cytokines TNF-α and IL -6 were significantly higher in OA compared with healthy controls." (PMID 37370001, 2023). "FMF patients with persisting arthritis often require different therapeutic agents including non-steroidal anti-inflammatory drugs, methotrexate and TNF-α inhibitors." (PMID 37752496, 2023). "Therefore, our study aimed to thoroughly investigate the effectiveness of anti-TNF from the onset of illness to 18 months in children with ERA using laboratory tests, MRI quantitative scoring, and the Juvenile Arthritis Disease Activity Score 27 (JADAS27)." (PMID 37303752, 2023). "Another central factor for arthritis TNFα does not show a consistent circadian expression pattern in RA patients." (PMID 37569682, 2023). "As TAS5315 ameliorated the arthritis score in an established mouse CIA model, we further measured whether TAS5315 reduced the levels of TNF-α, IL-1β, and IL-6 in synovial fluid exudates derived from the hind paws." (PMID 36821545, 2023). "Due to persisting arthritis and lack of funds for anti-TNF, he was initiated on tofacitinib 5 mg twice daily." (PMID 36855206, 2023). "Through a review of the English literature over the last 30 years, experts noted an increased risk of bacterial and mycobacterial infections in patients with arthritis treated with TNF inhibitors compared to non-biologic agents." (PMID 37554981, 2023).
Arthritis (continued). "In a retrospective study of patients with arthritis, tumor necrosis factor (TNF)α inhibitors administered from 3 to 15 months did not induce tumor progression." (PMID 36981837, 2023). "Bin cell “clogging” of efferent lymphatics is hypothesized to exacerbate inflammatory-erosive arthritis, as their removal with anti-CD20 B-cell depletion therapy in TNF-Tg mice restores lymphatic flow and ameliorates Advanced arthritis." (PMID 37691918, 2023). "While our study provides novel findings that αSMA+ PLV-LMC coverage is reduced in TNF-Tg mice with severe arthritis, and that this reduced coverage persists without turnover or recovery following effective anti-TNF therapy, our study has notable limitations." (PMID 35882971, 2022). "Furthermore, CP-25 alleviated kidney injuries in rats with arthritis through reducing the number of renal CD68+ cells and downregulating the levels of TNF-α and IL-6." (PMID 36457713, 2022). "An expert consensus on the use of TNF-α inhibitors in SSc among EUSTAR centers, which subjected arthritis might respond and should be conducted in more detailed investigation." (PMID 36408259, 2022). "Anti-TNF and methotrexate were discontinued and oral mesalazine was initiated with partial resolution of the diarrhea and no worsening of the arthritis." (PMID 36503523, 2022). "Hence, high frequency of TNF-α+CD4+ and TNF-α+CD8+ T cells existed, probably contributing to the pathogenesis of severe arthritis and pneumonitis in the collagen antibody-injected and ICI-treated humanized BALB/c-hPD1/hCTLA4 mice." (PMID 36016934, 2022). "TNF-α, IL-1β, and CXCL1 expression increased after IL-17 injection in an arthritis animal model." (PMID 36248896, 2022). "Furthermore, the levels of PGE2 and serum NO, activity of COX-2 and mRNA expressions of TNF, IL-6 and MMP-9 were downregulated, suggesting that AJR has pharmacological anti-arthritis activity." (PMID 36439173, 2022). "We observed the same trends in various arthritis patients on anti-TNF therapy, indicating that this change is neither disease nor drug specific." (PMID 35955616, 2022). "In effect, bone erosions in arthritis result from the combination of multiple signals that include high levels of RANKL in FLS, B, and T cells; the inflammatory cytokines TNFα, IL-1, and IL-6, both in RANKL dependent and independent pathways; and anti-CCP and other RA autoantibodies." (PMID 36032152, 2022). "Spare respiratory capacity (the difference between maximal and basal respiration rates) was significantly higher in resolving arthritis than veRA FLS, and was significantly reduced by TNFα treatment in healthy control and resolving synovitis FLS, but not in veRA FLS." (PMID 34512657, 2021). "We stimulated TNFα-pretreated OA- and RA-SF with 10–11 to 10–14 M PK2 and measured the cell culture medium concentration of the arthritis-aggravating factors IL-6 and MMP-3 and arthritis-inhibiting factors TIMP-1 and OPG." (PMID 34526577, 2021). "Genetically induced, spontaneous arthritis models such as SKG or TNFα-tg non-synchronously develop only at a certain age and thus cannot be used to address an arthritis-age-relationship." (PMID 34429153, 2021). "Eicosanoids derived from n-6 PUFAs influence the synthesis of pro-inflammatory cytokines, i.e., interleukin-1 (IL-1), interleukin-6 (IL-6), and tumor necrosis factor-α (TNF-α), which participate in the development of such skeletal disorders as osteopenia, osteoporosis, or arthritis." (PMID 34065038, 2021). "Our data suggest that synovial fluid lubricin, in addition to a panel of synovial fluid biomarkers, including TNF-α, CCL2, CCL11 and sGAG, may have potential for elucidating the progression of early joint inflammation." (PMID 33980227, 2021).
Arthritis (continued). "Physical activities such as running, walking, and jogging are proven to decrease this risk of cardiovascular complications among this sub-group of arthritis by reducing the pro-inflammatory leukotrienes such as Interleukin (IL)-6, C-reactive protein (CRP), tumor necrosis factor (TNF) alpha." (PMID 34722047, 2021). "It has been reported that arthritis-related genes of IL1β, IL6, and TNFα are expressed in the cartilage in AVNFH and could be potential biomarkers for AVNFH." (PMID 34305456, 2021). "Unlike TNF-α, IL-1β is absolutely required for disease development in K/BxN serum transfer arthritis." (PMID 34950033, 2021). "Supporting a predominant role for PAD2 in the joints, a study on PAD2- and PAD4-deficient mice showed that PAD2, but not PAD4, is required for tumor necrosis factor-α-induced arthritis and citrullination in the inflamed joints." (PMID 34737738, 2021). "The impressive anti-inflammatory effect of GSIs has been demonstrated also in these arthritis models; in both collagen induced arthritis (CIA) and collagen antibody-induced arthritis (CAIA), as well as in transgenic TNF-overexpressing (TNF-Tg) mice." (PMID 33912195, 2021). "Moreover, strychnine, brucine and triptolide possessed an anti-arthritis activity as they inhibited the proliferation of FLSs and reduced the production of TNF-α/IL-6 and mRNAs levels of TNF-α, IL-6, COX-2, and iNOS." (PMID 34108880, 2021). "Both IL-1β-induced synovitis and intra-articular lavage resulted in transient joint inflammation with elevations in synovial fluid TP, WBC count, and PGE2; however, increases in TNF-α and inflammatory chemokines CCL2, CCL3, CCL5, and CCL11 were predominantly restricted to synovitis joints only." (PMID 33980227, 2021). "Proinflammatory cytokines, such as IL-6 and tumor necrosis factor (TNF)-α, have been shown to sensitize nociceptors in rats, whereas TNF-α blockade attenuated pain behaviors and joint destruction in a mouse model of arthritis." (PMID 33808727, 2021). "Persistent pain in arthritis can continue without signs of peripheral inflammation due to altered expression of TNF-α in the dorsal root ganglia with nociceptor sensory neurons activation." (PMID 32849501, 2020). "Maslinic acid suppressed TNF-α production in RAW264.7 cells, and maslinic acid had anti-inflammatory effects in carrageenan-induced paw edema model, as well as anti-arthritis effects in mice models of arthritis." (PMID 32188443, 2020). "However, we did find bilateral hyperalgesia and raised serum cytokines TNFα, IL-7, and IL6 in arthritis mice." (PMID 32471455, 2020). "Therefore, the expression of activin A, MMP12 and TNFα designates the GM-CSF-dependent pro-inflammatory state of CD163+ ST macrophages in undifferentiated and established arthritis." (PMID 33679701, 2020). "For example, in the synovial fluid of BD patients with arthritis, lower levels of TNF-α than in rheumatoid arthritis patients are reported, possibly reflecting the less severe, non-erosive form of arthritis in BD." (PMID 32349254, 2020). "We treated FLS cells with the pro-inflammatory cytokines IL1β and TNFα in order to understand the cellular changes that occur when these FLS are subjected to higher-than-normal levels of these cytokines in vivo, for example, in arthritis." (PMID 32265733, 2020). "In an arthritis mouse model elicited by arthritogenic K/BxN serum, these mice developed severe inflammation in joints compared to control RAG1 knockout mice, which is mainly due to a major increase in TNF production." (PMID 32708595, 2020). "Development of arthritis requires local TNF production, as evidenced by the lack of joint changes in TNFΔARE mice with intestinal-specific TNF hyper-secretion." (PMID 32671059, 2020).
Arthritis (continued). "Recently, a pharmacological and docking studies on the influence of UA on adjuvant-induced arthritis reported that Ocimum sanctum L leaf extract (rich in UA) loaded nanostructured lipid carriers inhibited the COX-1, COX-2, IL-1, and TNF-α; hence, ameliorate the arthritis in rats." (PMID 32148658, 2020). "Indeed, plasma IL-6 levels have been reported to be extremely high in pre-arthritis patients and the CIA model of RA, whereas levels of TNFα tend to decrease with the onset of disease." (PMID 32634159, 2020). "We found that TNF plays important role in the development of arthritis induced by lupus IgG, but this result does not suggest that TNF is the therapeutic target in SLE patients." (PMID 32994999, 2020). "While RIP1 inhibition provided a similar benefit in anti-collagen antibody-induced arthritis model, there was no synergistic benefit in combining TNF and RIP1 inhibition." (PMID 32671059, 2020). "After years of exploration in the treatment of arthritis, there is still a lack of an efficient treatment, although TNF inhibitors have been widely used." (PMID 32958016, 2020). "IL-18Rα KO mice showed lower arthritis and histological scores in bone erosion and synovitis due to reductions in the infiltration of CD4+ T cells and F4/80+ cells and decreased serum IL-6, -18, TNF, and IFN-γ levels." (PMID 31861496, 2019). "In addition, the JBD patients who received anti-TNF-alpha therapy had higher serum CRP levels at the time of disease onset and higher rates of gastrointestinal symptoms and arthritis/arthralgia." (PMID 31296171, 2019). "It has been known that TNF-α induces p38 MAPK activation during the inflammatory response at the injured sites, and this induction is important for TNF-α-mediated bone destruction in arthritis." (PMID 31484360, 2019). "In addition, the immunologic changes of high levels of some cytokines (IL1, IL-10, TNF-α, and IL-17) and high CD4+/CD8+ T cell ratio are detected in arthritis and osteoarthritis samples." (PMID 31842790, 2019). "PlGF-2123-144-α-TNF did not suppress arthritis development in the untreated paw, indicating its localized efficacy." (PMID 31870429, 2019). "CD and UC/IBDU patients with arthritis/arthralgia were significantly more often treated with anti-TNF when compared to patients without arthritis/arthralgia." (PMID 31039159, 2019). "Our results demonstrated that the severity of arthritis was improved by suppressing serum inflammatory cytokines and the synovium cytokine mRNA expressions (especially those of IL-18, IFN-γ, TNF, and IL-6) and by suppressing the accumulation of CD4+ T cells in IL-18Rα KO mice." (PMID 31861496, 2019). "Compared with the patients who did not receive anti-TNF-alpha therapy, gastrointestinal symptoms (22.4 vs 66.7%; P = 0.041) and arthritis/arthralgia (24.5 vs 66.7%; P = 0.053) were more frequent in the patients who received anti-TNF-alpha therapy." (PMID 31296171, 2019). "In support of this, animal studies of experimental arthritis have reported the ability of TNF blockade to exert substantial effects in the CNS, including a reduction of astrocyte activation and TNFα-dependent activation of stress-induced kinases that are both coupled to altered nociception." (PMID 30770760, 2019). "Although mice in this group made a full recovery, the serum across the groups showed a high variation of IL-6, MCP-1 and TNF-α; therefore, no conclusion can be drawn as these are more likely to be the result of a cytokine storm than arthritis." (PMID 30713718, 2019). "RIP3 deletion affords more protection than MLKL deficiency in mouse models of renal injury, metastatic tumor, TNF-α challenge, arthritis and infection, supporting other non-necroptotic roles for RIP316,63–65." (PMID 31690718, 2019). "The arthritis-related genes IL1β, IL6 and TNFα were only found up-expressed in Ficat IV stage which indicated that the arthritis-related molecular changes were not significant in the progression of ONFH before Ficat III stage." (PMID 30671313, 2019).